MTOR (mechanistic target of rapamycin kinase)
Diseases named in the same sentence as MTOR in open-access papers (continued):
Sharing a sentence is not in itself a finding about the gene and the disease.
cancer (continued). "PI3K-Akt-mTOR is a major signaling pathway involved in cancer development and progression, which is pivotal in the regulation of aerobic glycolysis and tumor growth." (PMID 26918353, 2016). "Recently, many studies has shown several mechanisms associated with rapamycin resistance, which including promyelocytic leukemia (PML) gene, JAK2/STAT5, Notch1 and MAPK mediated resistance to mTOR-targeted therapies in cancer." (PMID 26872016, 2016). "As a whole, targeting the mTOR axis represents a potentially useful strategy for eradication of CSCs and reduction of tumor burden in selected type of cancer." (PMID 27826244, 2016). "The PI3K/Akt/mTOR signaling pathway plays a crucial role in cell growth, proliferation and survival and is frequently activated in human cancer." (PMID 26879559, 2016). "The centrality of mTOR as a node at which growth factors, hormones and nutrient inputs converge, in normal as well as in cancer cells, makes of it the most promising and, at the same time, the weakest of the possible targets." (PMID 27155197, 2016). "In agreement with our study, recent study has shown that PI-3K/mTOR inhibitor VS5584 preferentially target the aldefluor positive cancer stem cell compartment." (PMID 26938241, 2016). "The PI3K-Akt-mTOR pathway is known to be one of the critical regulators in cancer cells and proliferating cells." (PMID 27279169, 2016). "This factor, indeed, is able to facilitate PP2A-dependent dephosphorylation and degradation of c-Myc, in conditions in which autophagy is active whilst mTOR and cell proliferation, hence cancer development, are inhibited." (PMID 27083002, 2016). "Although the precise underlying mechanism(s) have not yet been fully elucidated, increasing evidence indicates that the P13K/Akt/mTOR pathway plays a crucial role in the survival and proliferation of cancer cells." (PMID 27223262, 2016). "In cancers where EGFR is rarely mutated, high EGFR activity can still be evident, resulting in hyperactive downstream MAPK and PI3K/AKT/mTOR signaling." (PMID 27221039, 2016). "Oncogenic activation of mTOR stimulates critical processes required for cancer cell survival, proliferation, angiogenesis and metastasis." (PMID 27624942, 2016). "Kinase signaling pathways, such as Ras/Raf/MEK and PI3-K/Akt/mTOR cascades, are generally hyperactivated and contribute to cancer cell proliferation, migration, invasion and chemoresistance." (PMID 27806324, 2016). "Despite the high efficiency in inhibiting the activity of both mTOR complexes, ATP-competitive mTOR inhibitors are still quite ineffective in our battle against cancer, potentially for several reasons." (PMID 27635236, 2016). "A similar study in other types of cancer cells treated with the dual PI3K/mTOR inhibitor NVP-BEZ235 demonstrated the expected inhibition of mTORC1 targets of p-4EBP1 and p-S6." (PMID 27391151, 2016). "Pyruvate kinase M2 (PKM2) is a key driver of aerobic glycolysis in cancer cells and has been shown to be up-regulated by mTOR in vitro." (PMID 27492148, 2016). "This study has been the first indicative of the role of miR-564 in cancer and also its association with MAPK, ErbB, mTOR and VEGF signaling pathways." (PMID 27600857, 2016). "In preclinical studies, a cytostatic effect of mTOR inhibitors has been reported in a variety of cancers." (PMID 27137757, 2016). "PI3K/AKT pathway acts as a positive regulator of the mTOR pathway, which serves as a negative regulator of autophagy in cancer cells, and disruption of the PI3K/AKT/mTOR pathway by anticancer agents induces autophagy." (PMID 26808193, 2016). "RAS/RAF/MEK/ERK is another frequently deregulated pathway in human cancer and coexists with mTOR activation." (PMID 27351224, 2016). "mTOR inhibition has already been proven a successful strategy for the control of tumor growth in different types of cancers." (PMID 27809291, 2016).
cancer (continued). "To note, c-Myc and RAS have also a prominent role in regulating the catabolic process of autophagy, of which the metabolic regulator mTOR is the major inhibitor, most likely responding to the new metabolic demands during cancer progression." (PMID 27083002, 2016). "The PI3K/AKT/MTOR pathway is an important signaling cascade in many different types of human cancer." (PMID 26943769, 2016). "The mammalian target of rapamycin (mTOR), a highly conserved serine/threonine protein kinase, is as a key regulator of cell growth, protein synthesis, metabolism homeostasis and cancer progression." (PMID 26958808, 2016). "Together, these results have established MTI-31 as a potent and selective inhibitor of mTOR enzymatic activity capable of targeting both mTORC1 and mTORC2 functions in cancer cells." (PMID 27563814, 2016). "We have recently reported that the monooxygenase NECAB3 and mTOR signalling also promote Mint3-mediated HIF-1 activation in cancer cells." (PMID 27883071, 2016). "mTOR inhibitors are most effective against cancer cells when used in combination with other therapies." (PMID 27391151, 2016). "Remarkably, the initial impact of inhibiting mTOR in normoxic cancer cells is the necrotic death of the hypoxic cells, which lack elevated levels of mTOR signaling." (PMID 27134166, 2016). "ILK/AKT/mTOR signaling pathway is widely known for modulating cell growth, differentiation, apoptosis, cellular metabolism and cancer cell survival." (PMID 27576342, 2016). "One of these classes consists of mammalian target of rapamycin (mTOR) inhibitors, a class of drugs with anti-proliferative effects supporting their role as anti-cancer agents." (PMID 27501793, 2016). "In recent years, numbers of clinical evidence have investigated the prognostic value of positive mTOR/p-mTOR expression in many common cancers, including ESCC." (PMID 27835987, 2016). "These experiments did, however, identify a synergy between CQ and AKT or mTOR inhibitors in FGFR-dependent cancers." (PMID 26853465, 2016). "Since many reports indicate that the 4E-BPs are functionally inactivated in cancer cells by major oncogenic signalling pathways, elucidation of the molecular mechanism involved in the mTOR-mediated regulation of 4E-BP degradation remains a major challenge." (PMID 26962866, 2016). "Ad-E1A12–induced AKT1 phosphorylation was PI3K-dependent in epithelial cancer cells, and mTOR-dependent in mesenchymal cancer cells." (PMID 27849011, 2016). "Given that mTOR-KIs target both mTORC1 and mTORC2, characterization of mTORC-regulated cancer cell growth, survival and metabolism will provide new insight into targeted cancer treatment." (PMID 27563814, 2016). "The phosphatidylinositol 3-kinase/protein kinase-B/mammalian target of rapamycin (PI3K/AKT/mTOR) signaling cascade is one of the most important intracellular pathways and is frequently activated in diverse cancers." (PMID 26658103, 2016). "BEZ235 reverses the hyperactivation of the PI3K/Akt/mTOR pathway, resulting in antitumor activities in cancers of various origins." (PMID 27507059, 2016). "Results obtained with other cancer models demonstrated that carnosine does also influence signal transduction pathways such as HIF-1alpha or Akt/mTOR/p70S6K." (PMID 27811375, 2016). "It is thought that targeting of mTORC1 and mTORC2 with mTOR-KIs will facilitate further dissection of molecular mechanism of mTOR complexes in cancer and a variety of age-related diseases." (PMID 27015560, 2016). "The mammalian target of rapamycin (mTOR) is a protein kinase of the PI3K/Akt signaling pathway with known critical role in cancer growth and tumor angiogenesis." (PMID 26686201, 2016). "The PI3K-Akt-mTOR signaling pathway has been identified as a key driver of carcinogenesis in several cancer types." (PMID 27589846, 2016).
cancer (continued). "On the other hand, a recent study showed that the expression of PI3K/AKT/mTOR proteins and mRNAs were increased following upregulation of the expression of miR-196b-5p in cancer cells." (PMID 27695061, 2016). "Based on the critical role of the PI3K/Akt/mTOR axis in the control of cell growth, metabolism and migration, components of this pathway represent attractive candidates for targeted cancer agents." (PMID 27489350, 2016). "We find the hub genes of the differential networks identified in the PI3K/AKT/mTOR pathway play an important role in cancer drug resistance." (PMID 27677586, 2016). "Successful development of mTOR-targeted cancer treatment will require molecular understanding of mTORC1 and mTORC2 in oncogenesis and therapy resistance." (PMID 27015560, 2016). "Conversely, the GSr-like signature is characterized by a strong activation of downstream targets of the EGFR and PI3K/mTOR pathway, which plays a critical role in cancer and, in particular, in GBM43." (PMID 26857460, 2016). "The finding that PKM2 phosphorylates S202/203 of AKT1S1 revealed a linkage between PKM2 overexpression and mTOR activation in cancer cells." (PMID 26876154, 2016). "On the other hand, aberrant mTORC1 and mTORC2 signaling via either genetic alterations or increased expression of proteins regulating mTOR and its downstream targets have contributed to cancer development." (PMID 27826244, 2016). "Through the activation of 5′-adenosine monophosphate-activated protein kinase (AMPK), metformin inhibits the expression of mammalian target of rapamycin (mTOR), which in turn prevents cell aging and cancer development." (PMID 27587088, 2016). "In our study, rhPGRN-treated HepG2 cells showed enhanced phosphorylation of mTORC1 downstream targets p70S6K, 4E-BP1 and mTORC2-dependent Akt Ser473, which provides the first evidence for PGRN-stimulated activation of mTOR signaling in human cancer cells." (PMID 26879559, 2016). "Inhibition of mTOR signaling often activates PI3Kinase/Akt pathway as a feedback mechanism in many cancers by up regulating insulin-like growth factor-1 receptor (IGF-IR) signaling." (PMID 27680387, 2016). "The PTEN tumor suppressor is the major negative regulator of the PI3K/mTOR pathway, which is one of the most frequently active pathways in human cancers, including HNSCC." (PMID 27285754, 2016). "Hypoxic cancer cells metabolize glucose and secrete lactate; normoxic, vessel-proximal cancer cells import and metabolize the lactate in a process involving mTOR signaling." (PMID 27134166, 2016). "Our findings show that 4E-BP3 is an important effector of mTORC1 and a robust predictive biomarker of therapeutic response to prolonged treatment with mTOR-targeting drugs in cancer." (PMID 27319316, 2016). "In fact, pan-mTOR inhibitors have been developed to treat cancer, so they are cytostatic and cytotoxic at intended anti-cancer concentrations." (PMID 28077803, 2016). "Continuous daily use of high dose mTOR inhibitors such as rapamycin in organ transplant or rapalogs in cancer treatment have resulted in IR, glucose intolerance, increase gluconeogenesis, and diabetes-like syndrome in a subset of patients." (PMID 27826244, 2016). "The data suggest that the normoxic cancer cells proximal to the few remaining vessels consume the available blood-borne glucose when mTOR is inhibited, thereby starving distal hypoxic cancer cells, leading to their demise." (PMID 27134166, 2016). "Given the inability of rapamycin to affect all functions of mTORC1 and its inefficacy in anti-cancer therapy, several academic and pharmaceutical laboratories have developed compounds that inhibit the catalytic activity of mTOR itself." (PMID 27635236, 2016).
cancer (continued). "Further, it has been shown that pharmacologic and biological inhibition of AKT/mTOR signaling suppressed cancer cell migration, invasion, and metastasis." (PMID 27602961, 2016). "Given that autophagy is critical in cellular homeostasis, our study not only clarifies the role of a dual PI-3K/mTOR inhibitor in autophagy, but also suggests that its autophagy inhibition needs to be considered if such an agent is used in cancer chemotherapy." (PMID 26814436, 2016). "mTOR has been considered as an attractive therapeutic target for cancer therapy in recent years and yielded profound effectiveness." (PMID 27026382, 2016). "As well as their effect on cancer which had developed already, mTOR inhibitors play even more significant roles in cancer prevention." (PMID 27462867, 2016). "Deregulation of the mTOR pathway is often observed in human cancers, which is consistent with its critical role in regulating cell growth and metabolism." (PMID 27510264, 2016). "Activation of the PI3K/Akt kinases leads to antiapoptosis, whereas inhibition of the PI3K/Akt/mTOR signaling pathway induces apoptosis of cancer cells." (PMID 27167344, 2016). "From recent studies, it has emerged that DHA can also simultaneously induce apoptosis and autophagy in cancer cells, and this process involves mTOR repression." (PMID 26821053, 2016). "Inhibitors of mammalian target of rapamycin (mTOR) work by interfering with protein kinases that modulate protein synthesis and cell proliferation in cancers." (PMID 26999120, 2016). "To demonstrate that we were able to detect cancer treatment response, tumors were treated with rapamycin, a potent inhibitor of the mammalian target of rapamycin (mTOR)." (PMID 27597137, 2016). "Consistent with a critical role in regulating cell growth and metabolism, dysregulation of the mTOR signaling is commonly observed in human cancers." (PMID 26940018, 2016). "Another important pathway is phosphoinoside 3 kinase/protein kinase B/mammalian target of rapamycin (PI3K/AKT/mTOR) cascade, which is constitutively activated in various cancers." (PMID 29083380, 2016). "In summary, mTOR inhibitors not only fail to kill TNBC cells but can also antagonize the cytotoxicity of most other anti-cancer compounds." (PMID 27165605, 2016). "The PI3K/AKT/mTOR signaling cascade is one of the most important intracellular pathways, which is frequently activated in different types of cancer." (PMID 27809261, 2016). "The deregulation of mTOR signaling is often observed in aging, metabolism, and cancer. mTOR interacts with several proteins to form 2 distinct complexes named mTOR complex 1 (mTORC1) and 2 (mTORC2)." (PMID 26886608, 2016). "Numerous cell growth factors and their receptors converge on the PI3K/Akt/mTor pathway and other intracellular pathways, which are widely activated in numerous cancers." (PMID 27509178, 2016). "The PI3K/Akt/mTOR pathway is constitutively activated in many different human cancers, including ovarian, breast, and colon cancers and glioblastoma." (PMID 27589687, 2016). "There has been evidence that aberrant expression of the Wnt pathway sensitizes cancer cells to an mTOR inhibitor; therefore, the use of a drug that targets both pathways would be even more effective than a single pathway inhibitor." (PMID 27888804, 2016). "Mechanistically, metformin indirectly activates AMPK signaling and subsequently inhibits mTOR activity, which is frequently increased in cancer cells." (PMID 27655692, 2016). "In order to tolerate oncogenic overexpression of MYC, cancer cells must undergo a major remodeling of metabolic and translational pathways- both of which are regulated by mTOR." (PMID 27438153, 2016).
cancer (continued). "The observed S6K inhibition at a high pimasertib dose (> 0.32 μM) on day 1 agreed with our previous finding of mTOR upregulation via ERK-dependent transcription in KRAS-mutant cancer cells." (PMID 27102436, 2016). "PI3K/AKT/mTOR signals have gained attention as potential therapeutic targets for several cancer types." (PMID 27165605, 2016). "Signaling pathways that are upstream or downstream of mTOR are commonly deregulated in human cancers." (PMID 27137757, 2016). "For the crucial role of mTOR in cancer cell biology, Several mTOR inhibitors have already undergone clinical trials for treating tumors, and the first identified inhibitor, rapamycin (from which mTOR derives its name), are currently in clinical development." (PMID 27612424, 2016). "Metabolic switch to aerobic glycolysis in cancer cells involves the mTOR-mediated expression of glycolytic enzymes through the activation of HIF-1α, NFκB, and c-Myc." (PMID 26918353, 2016). "Recent data has shown that the phosphoinositide 3-kinase (PI3-K)/Akt/mTOR pathway, and mTOR in particular, plays a critical role in the regulation of cancer metastasis." (PMID 27999314, 2016). "Mechanistic target of rapamycin (mTOR) is well known for inducing autophagy by inhibiting mTOR and also serves as an immunosuppressant in the treatment of cancer." (PMID 26752047, 2016). "The Ras/Raf/MEK/ERK and RAS/PI3K/PTEN/mTOR signal transduction pathways are well known regulators of cell proliferation and apoptosis which ultimately lead to drug resistance in various cancers including breast, hematopoietic and liver cancers." (PMID 26859684, 2016). "In particular, we pay our attention to the PI3K/AKT/mTOR pathway since it plays an important role in cancer drug resistance." (PMID 27677586, 2016). "It further highlights recent data on the continuous use of high dose rapamycin analogs and related second generation mTOR inhibitors for cancer eradication, for overcoming chemoresistance and for tumor stem cell suppression." (PMID 27826244, 2016). "It is also reported that FOXM1 can activate the PI3K/Akt/mTOR pathway which is one of dominant oncogenic pathways in human cancer." (PMID 26871945, 2016). "mTOR activation is commonly caused by oncogenic mutations in RAS/RAF/MAPK and PI3K/AKT pathways, and promotes cancer progression and therapeutic resistance." (PMID 27351224, 2016). "Gene ontology and pathway analysis illustrated potential roles of these targets in small-molecule metabolism, transcriptional regulation, RNA metabolism, proteoglycan synthesis in cancer, mTOR signaling pathway, or Wnt signaling pathway." (PMID 27899822, 2016). "We suggest that down-regulation of mTORC2-ACL axis reflects an important mechanistic aspect in mTOR-targeted cancer therapy." (PMID 27015560, 2016). "PKI-587, the most potent dual PI3K/mTOR inhibitor advanced to clinical development to date, suppresses the phosphorylation of PI3K/mTOR effectors and induces apoptosis in human cancer cell lines with elevated PI3K/mTOR signaling." (PMID 27438149, 2016). "Preclinical studies and clinical trials for the use of mTORC1 inhibitors such as rapamycin are an important avenue of research in the fight against cancers, as mTOR signaling is highly active in a number of different malignancies." (PMID 27231932, 2016). "The current focus on mTOR circuitry in cancers came from clinical failures of first generation mTOR inhibitors (rapamycin and its analogs), which mostly inhibit mTORC1 complex, but are ineffective due to feedback activation of mTORC2 complex." (PMID 26536665, 2016). "Overactivation of PI3K/Akt/mTOR pathway has been reported in many types of cancers offering a unique therapeutic target to design novel heterocycles against malignancies." (PMID 27097161, 2016). "Gene-sets such as “cell cycle”, “Wnt signaling pathway”, “mTOR signaling pathway” and cancer pathways such as “pathways in cancer” are all significant for the up-regulated genes." (PMID 27769251, 2016).